VHL (von Hippel-Lindau tumor suppressor)
Diseases named in the same sentence as VHL in open-access papers (continued):
Sharing a sentence is not in itself a finding about the gene and the disease.
retinal angiomas (11 papers, 2008 to 2025). "About 75% of VHL mutation carriers were diagnosed with at least one retinal angioma and 10% with at least 3 retinal angiomas." (PMID 31087189, 2019). "Patients with a family history of VHL who are younger or exhibit multifocal retinal angiomas should undergo genetic VHL testing as well as an initial and subsequent periodic systemic survey for non-ocular vascular and/or malignant tumors." (PMID 41377858, 2025). "Patients with VHL deletions were more prone to developing retinal angiomas." (PMID 28388566, 2017). "Deleted VHL gene may be restricted to stromal cells, suggesting that the stromal cells are the neoplastic component in the retinal hemangioma and may induce the accompanying neovascularization." (PMID 20029153, 2010). "Subsequently, we reported that a functional variant in the VHL target gene CCND1 influenced risk of retinal angiomas and central nervous system hemangioblastomas (but not RCC) in VHL disease patients." (PMID 19551141, 2009).
cervical carcinoma (10 papers, 2011 to 2026). A carcinoma arising from either the exocervical squamous epithelium or the endocervical glandular epithelium. "The VHL:c.292T>C (p.Tyr98His) variant was present in two unrelated individuals (ages 81 and 83) with bladder and cervical cancer." (PMID 40647474, 2025). "LIMD1 acts as a scaffold protein to bind PHD2 and VHL, which degrade HIF by ubiquitination and increased methylation of LIMD1 and VHL are associated with upregulation of HIF1-α in cervical cancer." (PMID 34631530, 2021). "Moreover, Cai et.al reported that miR-21-5p augmented the proliferation, migration, and invasion and inhibited apoptosis of cervical cancer cells through the downregulation of VHL." (PMID 36522730, 2022). "Human cervical cancer HeLa cells were exposed to 0.05% DMSO (vehicle control), hypoxia (1% O2), PHD inhibitor IOX2 or VHL inhibitor VH032 for 16 hours prior to profiling for global transcriptomic analysis using RNA seq." (PMID 30801039, 2019). "We further reveal that in two cervical cancer cell lines, the differences in HIF activity levels correlate with the level of the HIF cofactor, Hsp90, which protects HIF against VHL-independent degradation." (PMID 22132102, 2011). "We further show that in two cervical cancer cell lines, ME180 and HeLa, the different HIF activity levels observed correlate with the levels of hsp90, a cofactor that protects HIF against VHL-independent degradation." (PMID 22132102, 2011).
endolymphatic sac tumor (10 papers, 2011 to 2025). An aggressive epithelial neoplasm arising from the temporal bone. "Endolymphatic sac tumour (ELST) is known to be associated with Von Hippel Lindau (VHL) disease and sporadic tumours also show mutations in the VHL gene on the short arm of chromosome 3 (3p26.3)." (PMID 35397067, 2022). "Sporadic cases of endolymphatic sac tumor without VHL disease also showed VHL gene mutation similar to that in the germ line of patients with the disease according to Hamazaki's study." (PMID 22472343, 2012). "Preoperative testing for VHL genetic mutations, as well as fundus and abdominal ultrasonography or positron emission computed tomography (PET-CT), should be conducted as a standard practice for all patients diagnosed with or suspected of having endolymphatic sac tumor (ESLT)." (PMID 39871944, 2024).
multiple endocrine neoplasia type 2 (9 papers, 2006 to 2025). Multiple endocrine neoplasia type 2 (MEN2) is a multiple endocrine neoplasia, a polyglandular cancer syndrome characterized by the occurrence of medullary thyroid carcinoma (MTC), pheochromocytoma (PCC), in one variant, primary hyperparathyroidism (PHPT). "Approximately 89% of patients with bPHEOs develop multiple endocrine neoplasia type 2 (MEN2) caused by germline mutation of the RET (rearranged during transfection) proto-oncogene and von Hippel–Lindau (VHL) disease caused by the VHL gene." (PMID 36704524, 2022). "The whole-life incidence of PH and PGL is high in familial syndromes with these tumors: 1–5% in neurofibromatosis type 1 (NF1), 15–20% in VHL, 30–50% in multiple endocrine neoplasia type 2 (MEN-2), and probably more than 50% in SDHB and SDHD gene mutation carriers." (PMID 17156452, 2006).
neuroblastoma (9 papers, 2007 to 2025). Neuroblastoma (NB) is the most common solid, extracranial childhood tumor. "On the other hand, the predominance of HIF-2α is supported by previous observations performed in fetal paraganglia and neuroblastoma and by its upregulation at mRNA level in both VHL and SDH PH/PGL." (PMID 19763184, 2009). "Hypoxic treatment of neuroblastoma cells leads to their dedifferentiation towards a neural crest phenotype, while overexpression of VHL leads to their differentiation into functional neuron-like cells." (PMID 17655754, 2007). "These tumors are often associated with VHL mutations, which are absent in neuroblastoma and only observed in a restricted set of tumors associated with VHL syndrome." (PMID 41118218, 2025). "Neuroblastoma is not part of the clinical spectrum of VHL-associated neoplasms." (PMID 41118218, 2025). "This remarkable cancer-type specificity of HIF2α oncogenic activity reinforces the view that its role is highly context-dependent, and that in neuroblastoma, lacking VHL mutations, HIF2α may serve a different, potentially tumor-suppressive function." (PMID 41118218, 2025). "Hypoxia induces an immature phenotype of neuroblastoma cells, while inhibition of the HIF pathway by VHL overexpression mediates differentiation toward a neuron-like morphology." (PMID 17655754, 2007).
pulmonary hypertension (9 papers, 2016 to 2025). Increased pressure within the pulmonary circulation due to lung or heart disorder. "In a case report of a Bangladeshi infant carrying the p.Asp126Asn homozygous variant in the VHL gene severe pulmonary hypertension developed at 16 months of age and the patient died at 2 years of age due to the complications of a viral infection." (PMID 40130200, 2025). "When mice with either VHL or PHD2 mutations develop pulmonary hypertension, it is HIF-2α (via concomitant deletion) that has been shown to be the critical downstream effector." (PMID 37843154, 2024). "Since the identification of the CP mutation, other polycythaemic individuals with different missense mutations in both VHL alleles have been shown to have pulmonary hypertension and increased pulmonary vascular responses to hypoxia." (PMID 37843154, 2024). "It has been reported that VHL mutations cause pulmonary hypertension and pulmonary fibrosis in aged mice." (PMID 38760881, 2024). "Alternatively, the presence of pulmonary hypertension and right ventricular hypertrophy may have resulted in genetic remodeling in addition to that caused by the Chuvash VHL mutation." (PMID 27422990, 2016). "As the previous section demonstrates, VHL loss-of-function is a well-established upregulator of the HIF pathway that can lead to polycythaemia and pulmonary hypertension in euoxia." (PMID 37843154, 2024).
acute myeloid leukemia (8 papers, 2006 to 2025). Acute myeloid leukemia (AML) is a group of neoplasms arising from precursor cells committed to the myeloid cell-line differentiation. "It seems likely that development of acute myeloid leukemia in patient with VHL disease can be related to epigenetic alterations of the VHL gene, but further studies are needed." (PMID 23968328, 2013). "Through in silico evaluation, synthesis, binding affinity determination, and in vitro analysis, we identified two new VHL‐based PROTACs (2 and 9), which showed remarkable degradation of the protein of interest and antiproliferative activity in acute myeloid leukemia (AML) cells." (PMID 40343767, 2025). "We previously reported MA49 as a highly potent VHL‐mediated PROTAC candidate with potential for the treatment of FLT3‐ITD‐driven acute myeloid leukemia (AML)." (PMID 40223615, 2025). "The tumor type that included more targets was Acute Myeloid Leukemia (AML) where CRBN and VHL were the most frequently expressed ligases." (PMID 35249548, 2022).
cerebellar hemangioblastoma (8 papers, 2016 to 2025). A histologically benign tumor, usually cystic with a vascular mural nodule, that is most often found in the cerebellum though it has been reported at other sites within the neuraxis. "Sato reported the first case of 3p deletion syndrome combined with cerebellar angioblastoma in a child, which was mainly caused by a VHL gene deletion." (PMID 33643973, 2021). "The patient with a VHL mutation had cerebellar hemangioblastoma 6 years after bilateral adrenalectomy." (PMID 33584544, 2020). "The case was retrieved from a previous study in which a 40-year-old male had been diagnosed with hemangioblastoma of the cerebellum and renal oncocytoma with a germline VHL mutation." (PMID 30728892, 2019). "The phospho‐S6 ribosomal protein in the mTOR pathway is a potential target in VHL‐related cerebellum hemangioblastomas." (PMID 31317677, 2019).
gastric cancer (8 papers, 2017 to 2026). A primary or metastatic malignant neoplasm involving the stomach. "Additionally, VHL‐mediated downregulation of NIMA‐associated kinase 8 (NEK8) inhibited gastric cancer cell proliferation and migration." (PMID 40576306, 2025). "Similarly, the reduction in gastric cancer cell invasion caused by VHL was restored by the overexpression of SYT11 and SPINK1." (PMID 40576306, 2025). "Western blotting confirmed VHL protein expression in gastric cancer cell lines, whereas Parkin was undetectable (data not shown)." (PMID 40576306, 2025). "The present study demonstrates that VHL inhibits gastric cancer cell proliferation and invasion by promoting proteasome‐dependent degradation of SYT11, thereby downregulating SPINK1." (PMID 40576306, 2025). "Given the low expression of Parkin and high expression of VHL in gastric cancer cell lines, we investigated the role of VHL in regulating SYT11 expression." (PMID 40576306, 2025). "We compared the expression levels of Parkin and another E3 ligase, VHL, in gastric cancer cell lines." (PMID 40576306, 2025). "The VHL‐induced reduction in gastric cancer cell growth and invasion was rescued by overexpression of SYT11 and SPINK1." (PMID 40576306, 2025). "Analysis of the Cancer Dependency Map (DepMap) showed low Parkin mRNA expression in most gastric cancer cell lines, while VHL mRNA expression was elevated." (PMID 40576306, 2025). "Despite these promising results, the molecular substrates and downstream mechanisms of VHL in gastric cancer remain incompletely understood." (PMID 40576306, 2025). "Finally, we evaluated the role of SYT11 and SPINK1 in VHL‐mediated inhibition of gastric cancer cell growth." (PMID 40576306, 2025). "Next, we investigated the effect of VHL on SYT11 expression in gastric cancer cells." (PMID 40576306, 2025). "These analyses suggest that VHL may inhibit gastric cancer cell growth by suppressing SYT11 protein expression." (PMID 40576306, 2025). "Additionally, it will be important to investigate the combined effects of HIF‐1α, a VHL target, and SYT11 on the growth, migration, and invasion of gastric cancer cells following VHL inhibition." (PMID 40576306, 2025). "VHL expression is negatively correlated with SYT11 expression in gastric cancer patients." (PMID 40576306, 2025). "In SYT11‐transfected gastric cancer cells, VHL reduced SYT11 protein expression and its half‐life." (PMID 40576306, 2025). "Furthermore, SPINK1 knockdown inhibited the growth and invasion of gastric cancer cells, mirroring VHL overexpression effects." (PMID 40576306, 2025). "Recent findings demonstrate the potential of VHL in targeting gastric cancer." (PMID 40576306, 2025). "Although VHL is a known tumour suppressor, its role in gastric cancer remains unclear." (PMID 40576306, 2025). "Suggestive variants of uncertain significance were identified, including a chromosome 3 inversion affecting VHL and MLH1 in a patient with renal and gastric cancers." (PMID 41990296, 2026). "The VHL isoform with short 3′‐UTR inhibits cell growth and enhances apoptosis in gastric cancer cells." (PMID 40576306, 2025). "VHL and SYT11 contribute to gastric cancer progression via distinct pathways, but both are involved in the ubiquitin–proteasome system, suggesting possible convergence in post‐translational control." (PMID 40576306, 2025). "Analyses of public data confirmed that high expression of VHL and low expression of SYT11 are positively correlated with improved prognosis of gastric cancer patients." (PMID 40576306, 2025). "In this study, we have uncovered a novel mechanism by which VHL decreases SYT11 protein stability, thereby downregulating SPINK1 expression and inhibiting the growth and invasion of gastric cancer cells." (PMID 40576306, 2025). "This study investigates whether von Hippel–Lindau (VHL), an E3 ligase, regulates the stability of synaptotagmin 11 (SYT11) protein in gastric cancer cells." (PMID 40576306, 2025).
gastric cancer (continued). "Specifically, a VHL‐recruiting vascular endothelial growth factor receptor 2 (VEGFR‐2) PROTAC (proteolysis‐targeting chimera) was shown to degrade VEGFR‐2 protein, inducing apoptosis in gastric cancer cells." (PMID 40576306, 2025).
hemangioma (8 papers, 2014 to 2025). A benign vascular lesion characterized by the formation of capillary-sized or cavernous vascular channels. "Further investigation revealed capillary retinal angiomas and hemangiomas of the brain and spine typical of VHL disease, and he was diagnosed with a de novo, germline nonsense mutation in exon 3 of the VHL gene." (PMID 25159823, 2014). "Notably, additional hypermethylation of tumor suppressor genes causes the inactivation of VHL alleles, leading to VHL-associated hemangiomas, highlighting the potential role of epigenetic modification, particularly HDAC inhibitors, in disease progression." (PMID 39934895, 2025). "A solitary juxtapapillary angioma finding should prompt a screen for VHL, which is best detected by molecular genetic diagnostics." (PMID 31588386, 2019). "Regular screening to identify the development of new angiomas and early diagnosis of VHL may facilitate greater treatment success." (PMID 31588386, 2019).
hereditary leiomyomatosis and renal cell cancer (8 papers, 2017 to 2024). Hereditary leiomyomatosis and renal cell cancer (HLRCC) is a hereditary cancer syndrome characterized by a predisposition to cutaneous and uterine leiomyomas and, in some families, to renal cell cancer. "There are different types of kidney cancers, as for example von Hippel–Lindau (VHL), heredity papillary renal carcinoma (HPRC), Birt–Hogg–Dubé (BHD), hereditary leiomyomatosis renal cell carcinoma (HLRCC), succinate dehydrogenase kidney cancer (SHD-RCC), and so on." (PMID 28854935, 2017).
Hypertension (8 papers, 2011 to 2025). The presence of chronic increased pressure in the systemic arterial system. "Verified risk factors for RCC include age, smoking, obesity, poorly controlled hypertension, diet, alcohol, and environmental and genetic factors (i.e., VHL mutations)." (PMID 34439368, 2021). "High blood pressure (p = 0.16), family history of cancer (p = 0.12), and fruit intake frequency (p = 0.09), were inversely associated with VHL promoter hypermethylation and were selected for initial inclusion in multivariate models." (PMID 22022277, 2011). "Therefore, beyond the specific context of VHL, this case advocates for a heightened index of suspicion for secondary hypertension in clinical practice." (PMID 41164131, 2025). "To our knowledge, we are the first to study gene-environment interactions between the selected VHL and HIF1A SNPs and smoking, hypertension, BMI and alcohol consumption." (PMID 31924838, 2020). "In addition, interactions between VHL and HIF1A SNPs and smoking, hypertension, body mass index (BMI) and alcohol consumption were studied." (PMID 31924838, 2020).
leukemia (8 papers, 2018 to 2024). A malignant (clonal) hematologic disorder, involving hematopoietic stem cells and characterized by the presence of primitive or atypical myeloid or lymphoid cells in the bone marrow and the blood. "753B PROTAC, which causes BCL-XL/BCL-2 ubiquitination and selective degradation of cells expressing VHL, is an innovative approach to inducing apoptosis activation and eliminating chemotherapy-induced senescent leukemia cells." (PMID 36291779, 2022). "To determine if this difference in essentiality is reflected in differential resistance acquisition, we focused on two BET Bromodomain targeting PROTACs: dBET6 (CRBN-based) and ARV-771 (VHL-based) that have matched cellular potency, including in the near-haploid human leukemia cell line KBM7 26,27." (PMID 36329119, 2023). "Zhou and his coworkers linked ABT263 to VHL ligand to develop the PROTAC DT2216, which effectively degraded Bcl-xL and suppressed Bcl-xL-dependent leukemia cells in vitro and in vivo, without causing thrombocytopenia due to the poor expression of VHL in platelets." (PMID 35410300, 2022). "Associating these studies with the fact that PROTAC DT2216 has a limited effect on other types of leukemia than BCL‐XL‐dependent T‐ALL, Zhou's group has invested in developing a series of new VHL‐based PROTACs, which use the same TLM as the DT2216 (navitoclax)." (PMID 38845697, 2024). "Using this approach to guide our development of a series of ABT263-derived and VHL-recruiting PROTACs, we generate a potent BCL-xL and BCL-2 (BCL-xL/2) dual degrader with significantly improved antitumor activity against BCL-xL/2-dependent leukemia cells." (PMID 34824248, 2021). "In addition to this compound being cytotoxic against BCL‐XL dependent leukemia cell line (MOLT‐4 cells), with a DC50 value of 63 nM and a Dmax value of ∼91%, it was shown to be less toxic to platelets than the respective TLM alone, given the low expression of VHL on platelets." (PMID 38845697, 2024).
multiple endocrine neoplasia type 1 (8 papers, 2020 to 2024). An autosomal dominant tumor predisposition syndrome caused by pathogenic variants in the MEN1 gene, characterized by an increased risk of tumors of the parathyroid glands, pituitary gland, and foregut neuroendocrine tumors (most commonly pancreatic islet cells). "Ten percent of PNETs present in association with genetic syndromes including Multiple Endocrine Neoplasia Type I (MEN-1), Neurofibromatosis Type 1 (NF-1), TSC, and von Hippel-Lindau (VHL)." (PMID 33897589, 2021). "PNETs can be sporadic or familial genetic syndromes, including multiple endocrine neoplasia-1 (MEN-1), von-Hippel Lindau (VHL), neurofibromatosis-1, tuberous sclerosis (TS)." (PMID 32899271, 2020).
multiple myeloma (8 papers, 2014 to 2023). "Two previous studies demonstrated that VHL-CRBN heterodimerizing PROTACs promote CRBN degradation, but not VHL degradation, and that treatment with these PROTACs causes resistance of multiple myeloma cells to IMiDs31,32." (PMID 31873151, 2019). "In addition, wogonin also represses multiple myeloma-stimulated angiogenesis through c-Myc/von Hippel-Lindau tumor suppressor (VHL)/HIF-1α signaling pathway, LPS- and H2O2-induced angiogenesis through PI3K/Akt/NF-κB pathway." (PMID 31719837, 2019). "This issue could be overcome by either hijacking two different E3 ligases, CRBN and VHL, or a PROTAC, such as YKL-06-102, that simultaneously targets IKZF1, IKZF3, and CDK6, achieving intramolecular synergistic effects even in IMiD-insensitive multiple myeloma cells." (PMID 35197447, 2022).